MTOR (mechanistic target of rapamycin kinase)
Diseases named in the same sentence as MTOR in open-access papers (continued):
Sharing a sentence is not in itself a finding about the gene and the disease.
autism (continued). "Abnormalities in mTOR activity are linked with severe nervous system development deficits, including tumors, autism, and seizures." (PMID 34830376, 2021). "Mutations in the TSC1/TSC2 genes lead to the overactivation of mTOR signalling, which is also linked to nonsyndromic autism." (PMID 34576223, 2021). "Genes linked with the development of autism include mTOR genes as well as those implicated in modulating the balance between excitatory and inhibitory neurotransmission, cerebral connections, and synaptic plasticity." (PMID 34308255, 2021). "A substantial part of both syndromic and idiopathic autism cases can be attributed to disorders caused by mTOR-dependent translation deregulation." (PMID 34065644, 2021). "Complete loss of TSC1 or TSC2 leads to excessive mTOR activity, and mutations in other components of the mTOR pathway are also linked to autism in humans such as PTEN, RHEB, and MTOR." (PMID 33054857, 2020). "Dysregulation of mTOR signaling pathway has been shown to have a pathogenic role in a variety of neurological disorders including autism." (PMID 32443912, 2020). "The study suggested that the down-regulation of Akt/mTOR pathway in autism is likely to affect spine and cortical circuits implicated in higher cognitive function and behavior, thus causing autistic phenotypes." (PMID 32443912, 2020). "Here, we characterized autism predisposition genes by dividing them into four categories directly or indirectly related to the mTOR signaling pathway." (PMID 31847491, 2019). "The mTOR inhibitor rapamycin has rescued not only the synaptic plasticity but also the behavioral deficits in adult mice with syndromic autism, a heterozygous, inactivating mutation in the TSC2 gene." (PMID 31847491, 2019). "mTOR signaling has been found to have a pathogenic role in a myriad of neurological disorders, such as epilepsy, autism, intellectual disability, dementia, traumatic brain injury, brain tumors, and hypoxic-ischemic injury." (PMID 31847491, 2019). "A significant part of both syndromic and idiopathic autism cases can be attributed to disorders caused by the mechanistic target of rapamycin (mTOR)-dependent translation deregulation." (PMID 31847491, 2019). "On the postsynaptic site, hyperactivated mTOR, hence, impaired autophagy, has been linked to reduced developmental dendritic pruning causing autism‐like neurodevelopmental disorders." (PMID 28884504, 2018). "Abnormalities in mTOR activity is linked with severe deficits in nervous system development, including tumors, autism, and seizures." (PMID 29789464, 2018). "mTOR inhibition by rapamycin corrects developmental spine pruning defects in mice mutant for autism‐causing Tsc2." (PMID 28884504, 2018). "In all of the examples given above, inability to downregulate mTOR-signaling is associated with the autism phenotype." (PMID 28420080, 2017). "Multiple autism risk genes converge on the regulation of mTOR signalling, which is a key effector of neuronal growth and connectivity." (PMID 27845329, 2016). "Accordingly, mTOR/p70S6K pathway has been linked to synaptic plasticity and neurogenesis, and mTOR signaling impairment has been related to neurodegenerative disorders, including autism and AD." (PMID 27379018, 2016). "This supports the idea that mTOR pathway deviations in either direction can adversely affect establishment, maintenance and function of neural networks and thus ultimately cause autism’s cognitive and behavioural deficits." (PMID 25627160, 2015). "Epidemiological findings and animal models have indicated that excessive signaling through the mTOR pathway increases the risk of autism." (PMID 26218250, 2015). "Mutations in genes linked to autism adversely affect molecules regulating dendritic spine formation, function and plasticity, and some increase the mammalian target of rapamycin, mTOR, a regulator of protein synthesis at spines." (PMID 25627160, 2015).
autism (continued). "Gene mutations of phosphatase and tensin homolog (PTEN), the negative regulator of the mammalian target of rapamycin (mTOR), have been linked to higher risk of autism, but also to increased proliferation and function of mast cells." (PMID 22747567, 2012). "These preliminary findings indicate that H3R antagonist E159, which maintains crucial interactions in docking studies at H3R, could play a role in regulating the mTOR signaling pathway associated with autophagy and improve autism-like symptoms." (PMID 39458934, 2024). "Importantly, our study indicates that ASD NPCs not only have enrichment of dysregulated mTOR but that mTOR dysregulation is driving autism-associated phenotypes." (PMID 38525876, 2024). "Moreover, a substantial proportion of autism predisposition genes directly or indirectly intersect with mTOR signaling activity." (PMID 38138941, 2023). "Furthermore, whole exome sequencing of patients with macrocephaly and autism has uncovered mutations other than PTEN that localize to the PI3K-Akt–mTOR pathway." (PMID 37799731, 2023). "Notably, approximately 8–10% of autism cases have been associated with abnormalities in the mTOR signaling pathway." (PMID 38138941, 2023). "Dysregulation in the mTOR pathway could contribute to aberrant synaptic protein synthesis and induce autism development, and cause ASD-associated syndromes such as macrocephaly, seizures and learning deficits." (PMID 35422816, 2022). "A significant part of both syndromic and idiopathic autism cases could be attributed to disorders caused by mammalian target of rapamycin (mTOR)-dependent translation deregulation." (PMID 35055151, 2022). "Given the central role of mTOR for the stabilization of inhibitory synapses dependent on Met signaling, it is conceivable that Tsc2, another autism risk gene and negative regulator of mTOR, might also be involved in gephyrin clustering." (PMID 34054427, 2021). "Our findings causally link mTOR-related synaptic pathology to large-scale network aberrations, revealing a unifying multi-scale framework that mechanistically reconciles developmental synaptopathy and functional hyperconnectivity in autism." (PMID 34667149, 2021). "None out of 992 ASD genes and 871 AID genes fell into all four examined categories, but 54 genes that associated with autism and autoimmune disorders simultaneously were of particular interest, with the largest number of intersections observed for mTOR-modulated genes." (PMID 34065644, 2021). "Modulation of this pathway could offer benefits for syndromic autism linked to aberrant mTOR signaling." (PMID 32443912, 2020). "Thus, we characterized 58% of autism predisposition genes by dividing them into categories based on their association in the mTOR signaling pathway and vitamin D sensitivity." (PMID 31847491, 2019). "The mTOR system is critical for neuronal development and a causative role of mTOR system dysfunction has been proposed for better understood neurodevelopmental disorders, such as Fragile X, autism, schizophrenia, and drug addiction." (PMID 30049952, 2018). "In line with this, mTOR-dependent impairment of autophagy is implicated in various neuropsychiatric disorders such as dementia, movement disorders, motor neuron disease, seizures, brain ischemia, autism, affective disorders, addiction, and schizophrenia." (PMID 30061532, 2018). "Tuberous sclerosis complex 1 (Tsc1) suppresses mTOR signaling, and loss of function mutations of Tsc1 cause tumors and a variety of neurological symptoms including intellectual disability, seizures, and autism." (PMID 29163060, 2017). "The mTOR inhibitor, rapamycin, has been shown to be effective to rescue some phenotypes caused by these mutations and has been used as a therapeutic agent to treat some of the autism symptoms." (PMID 27909399, 2016). "This hypothesis is based on previous studies that found gene mutations in the PI3K/mTOR pathway in monogenic and idiopathic forms of autism." (PMID 26770665, 2016).
autism (continued). "Our results suggest that functional analysis of PI3K/mTOR signaling is a biomarker tool to identify disease-associated molecular defects that could serve as therapeutic targets in autism." (PMID 26770665, 2016). "Furthermore, epidemiological findings and animal models have indicated that excessive signaling through the mTOR pathway leads to an increased risk of autism." (PMID 26218250, 2015). "Indeed, mutations in genes encoding Akt-mTOR cascade components cause disorders with high rates of autism." (PMID 25627160, 2015). "In addition, mutations in the downstream mTOR target eukaryotic translation initiation factor 4E (eIF4E) have also been associated with autism." (PMID 24379984, 2013). "Thus, the mTOR pathway forms a highly connected signaling network linked to autism." (PMID 33054857, 2020). "Taken together, mTOR pathway deviations in either direction were postulated to adversely affect the establishment, maintenance and function of neuronal networks that could ultimately cause autism cognitive and behavioral deficits." (PMID 32443912, 2020). "Moreover, this could be the cause of autistic disorders and other neuropsychiatric diseases, since one of the characteristics of these conditions is the hyperactivity of the mTOR signaling pathway." (PMID 32921299, 2020). "We hypothesized that genetic and/or environment mTOR hyperactivation, including provocation by vitamin D deficiency, might be a common mechanism controlling the expressivity of most autism predisposition genes and even core symptoms of autism." (PMID 31847491, 2019). "Isoflurane was found to over-activate the mechanistic target of rapamycin (mTOR) pathway, a signaling system critical for normal development, which has been implicated in neurodevelopmental disorders in which cognitive function is affected, including autism and fragile X mental retardation." (PMID 28683067, 2017). "This confirms previous genetic studies suggesting that defects in the PI3K/mTOR pathway may be a shared pathomechanism in a sub-cohort of individuals with autism, in addition to the known syndromic cases associated with altered PI3K/mTOR signaling (such as FXS, TS, and NF-1)." (PMID 26770665, 2016). "Notably, one pioneering study has identified a mutation in the EIF4E promoter in autism families, implying that deregulation of downstream mTOR signaling (eIF4E) could be a novel mechanism for ASDs." (PMID 23533374, 2013). "Studies show that idiopathic autism is characterized by reduced TrkB signaling through the PI3K/Akt/mTOR pathway and via the Eps8/Rac pathway." (PMID 40149774, 2025). "AKT/mTOR is a biological substrate for autism, and mTOR is involved in synaptic plasticity, neuronal development and memory storage in the CNS." (PMID 40568709, 2025). "The mTOR pathway, pivotal for protein synthesis and brain homeostasis in autism, represents a potential link between immune disturbances and behavioral deficits." (PMID 41346380, 2025). "From a mechanistic point of view in autism, the activity of TGFB signaling genes is tightly linked to mTOR, whose increased expression affects TSC1 (a partner of HAP1) linked to autism neuropathology." (PMID 38994948, 2024). "An aberrant mTOR pathway can lead to a severe deficit in nervous system development, including tumors, autism, and seizures." (PMID 38812794, 2024). "mTOR signaling alterations were confirmed in all NPCs across both ASD subtypes, and mTOR modulation rescued ASD phenotypes and reproduced autism NPC-associated phenotypes in control NPCs." (PMID 38525876, 2024). "Upregulation of the PI3K-AKT/mTOR signaling pathway involves many human brain abnormalities, including autism, and it is a suggested target to treat ASD." (PMID 39597837, 2024). "Surprisingly despite the genetic heterogeneity, hundreds of shared p-peptides were identified between autism subtypes including the mTOR pathway." (PMID 38525876, 2024).
autism (continued). "Previous studies have pointed out that disruption of mammalian target of rapamycin (mTOR)-regulated macroautophagy and autophagy leads to autism-like abnormalities." (PMID 37200987, 2023). "A study showed that in autism mice models, synaptic alterations dependent on mTOR lead to a distinctive functional hyperconnectivity signature, and this effect can be reversed by inhibiting mTOR." (PMID 38138941, 2023). "In the context of APPIN5, EIF4E serves as a hub protein within the autism network, while also being closely interconnected with the mTOR signaling pathway and the circadian clock." (PMID 37807632, 2023). "Relevance of human illness in mTOR, which is increasingly recognized in oncology, neurology, immunology, and biotransformation/metabolisms, including autism." (PMID 36672623, 2023). "Considering that the imbalance of autophagy is closely associated with cerebral diseases including autism, Western blot was employed for measuring the protein levels of LC3 I, LC3 II, p62, mTOR, and p-mTOR in the hippocampal tissues." (PMID 37200987, 2023). "This narrative review analyzes both bioinformatic and experimental evidence that connects mTOR signaling to the maternal autoantibody-related (MAR) autism spectrum and autoimmune neuropsychiatric disorders simultaneously." (PMID 35055151, 2022). "The frequent incidence of autism in the monogenetic mTORopathies has advocated a critical role for mTOR in the pathogenesis of autism." (PMID 36045116, 2022). "It has been shown that deregulation of the mTOR signaling pathway plays a role in the pathogenesis of many neurological disorders, such as epilepsy, autism, mental retardation, Alzheimer’s disease, and brain tumors." (PMID 35055151, 2022). "The frequent incidence of autism in the monogenetic mTORopathies suggests a critical role for mTOR in the pathogenesis of autism." (PMID 35682995, 2022). "In the future, it would be important to identify the developmental stages crucial to autism when the crosstalk between mTOR and the clock is most consequential." (PMID 36045116, 2022). "Several other autism risk factors are also associated with cancer, including PTEN, and components of the mTOR and Ras-MAPK pathways." (PMID 36222238, 2022). "This review analyzes autoimmune disorders leading to autism-like behavior, their connections with abnormal mTOR activity, and approaches to their diagnosis for subsequent immunomodulatory therapy." (PMID 35055151, 2022). "We focused on the mTOR pathway as hyperactive mTOR signaling has been identified in the cortex of autism subjects." (PMID 35113852, 2022). "A further large subcluster is related to intracellular signaling, which includes important autism genes such as mTOR being a central component of cell growth." (PMID 35948596, 2022). "Treatment with mTOR inhibitors was also demonstrated to be effective in experimental models of autism." (PMID 34576223, 2021). "Further, our cell-based data is consistent with the recent addition of PPP2R5D to the list of autism susceptibility genes related to AKT3, PIK3CA, PTEN, TSC1/2, and mTOR." (PMID 33482199, 2021). "Dysregulation of the mTOR pathway occurs in numerous neurodegenerative and neurodevelopmental diseases including AD and autism." (PMID 34290083, 2021). "A hyperactive mTOR pathway, as a result of Tsc2 insufficiency, is probably responsible for the autism-related symptoms in TSC." (PMID 34576223, 2021). "For example, chemotherapeutic agents that inhibit PTEN signaling or related pathways, such as PI3K-AKT, mTOR and NF-1 (e.g., rapamycin and everolimus), are potential candidates for treating several manifestations of autism." (PMID 31007884, 2019). "Whereas autism is characterized by increased PI3K-Akt-mTOR activity, a substantial body of evidence indicates that this pathway is downregulated in schizophrenia." (PMID 31548888, 2019).
autism (continued). "BTBR is an inbred strain model of forms of idiopathic autism in which reduced inhibitory neurotransmission and excessive mTOR signaling have been reported." (PMID 30653853, 2019). "An important role for upregulation of the PI3K-Akt-mTOR in autism more generally is indicated by significant higher pathway activity in cells of individuals with idiopathic autism, than in matched controls." (PMID 31548888, 2019). "The mTOR anabolic biochemical pathway is of great interest in autism and in macrocephaly and autism." (PMID 31024350, 2019). "mTOR activity is also increased in the valproic acid rodent model of autism, with alleviation of symptoms by administration of the mTOR antagonist rapamycin." (PMID 31548888, 2019). "Gene defects associated with upstream regulators of mTOR (TSC1, TSC2, and PTEN), are associated with autism and in many cases, macrocephaly." (PMID 31024350, 2019). "Schizophrenia thus shows an opposite pattern to autism with regard to PI3K-Akt-mTOR pathway activation." (PMID 31548888, 2019). "This drug inhibits mTOR, one of the top 30 super-pathways identified with high scores when comparing shared autism and cancer genes." (PMID 30866437, 2019). "PTEN is an important negative regulator of the AKT/mTOR signaling pathway; neurologically, heterozygous PTEN variants are associated with macrocephaly and syndromic autism (PTEN hamartoma tumor syndrome – PHTS)." (PMID 31847491, 2019). "Studies in mouse models of autism that alter the upstream elements of the mTOR pathway recapitulate cortical malformations." (PMID 29789464, 2018). "TSC2 is directly involved in regulating mTORC1 downstream of AKT, and autism-linked mutations in TSC2 cause increased mTOR activation and a de-coupling of mTOR from AKT." (PMID 30237867, 2018). "The mTOR pathway has already gained significant attention in connection to autism due to its significant involvement in syndromic autisms." (PMID 28420080, 2017). "Dysregulated PI3K/mTOR signaling in the brain has been detected and successfully targeted to correct phenotypes in several mouse models of autism, including FXS." (PMID 26770665, 2016). "In particular, we performed quantitative analyses of phosphorylation of the PI3K/mTOR downstream target S6 in patient cell lines from the Autism Genetic Research Exchange (AGRE) collection and in proband-sibling pairs from the Simons Simplex Collection (SSC)." (PMID 26770665, 2016). "Based on current published data, it is difficult to estimate what the prevalence of autism with PI3K/mTOR signaling defects is." (PMID 26770665, 2016). "In summary, our study is the first to demonstrate major decreases in protein expression and phosphorylation for mTOR and components of its downstream signaling pathways in subjects with idiopathic autism." (PMID 25627160, 2015). "In contrast to some monogenic disorders with high rates of autism, our data demonstrate down-regulation of the Akt/mTOR pathway, specifically via p70S6K/eIF4B, in idiopathic autism." (PMID 25627160, 2015). "We measured protein levels of mTOR and its upstream/downstream effectors in brains from subjects with idiopathic autism versus control subjects and in VPA- versus saline-exposed rats." (PMID 25627160, 2015). "mTOR complex 1 (mTORC1) and mTOR complex 2 (mTORC2) are two distinct complexes with mTOR, which are also involved in autisms and ADHD." (PMID 25647412, 2015). "There is also evidence supporting dysregulation of upstream activators of the ERK1/2 and mTOR pathways in autism, including BDNF signaling through the TrkB receptor (Maija Castrén and Castrén, 2014)." (PMID 26483618, 2015). "This section will cover these key molecular readouts of growth in autism, including dysregulated growth factor, mammalian target of rapamycin (mTOR), and extracellular signal-regulated kinase (ERK1/2) signaling." (PMID 26483618, 2015).